RIPK3 (receptor interacting serine/threonine kinase 3)
Diseases named in the same sentence as RIPK3 in open-access papers (continued):
Sharing a sentence is not in itself a finding about the gene and the disease.
cervical carcinoma (continued). "Because C4-I cells are derived from a cervical squamous cell carcinoma (SCC) and HeLa is an adenocarcinoma cell line, we were interested in the in vivo expression patterns of RIPK3 in both human cervical cancer entities." (PMID 25888634, 2015). "Our in situ analyses of human cervical cancer specimens revealed heterogeneous RIPK3 expression patterns in cervical SCCs and adenocarcinomas." (PMID 25888634, 2015). "We unraveled the kinase RIPK3 as the critical determinant for IL-1α release and for the DC-stimulatory capacity of PolyIC-treated cervical cancer cells." (PMID 25888634, 2015). "This study demonstrates for the first time that potent induction of immunostimulatory necroptotic cell death is feasible in cervical cancer cells and requires the expression of RIPK3." (PMID 25888634, 2015). "In summary, our study identified a novel RIPK3-dependent mechanism that explains how PolyIC-treatment of cervical cancer cells leads to potent DC activation." (PMID 25888634, 2015). "Our in vivo analyses in cervical cancers revealed that RIPK3 is expressed in all SCCs investigated thus far, at varying levels ranging from weak to strong." (PMID 25888634, 2015). "Here, we demonstrate that stimulation of cervical cancer cells with PolyIC induced necroptotic cell death, which was strictly dependent on the expression of the receptor-interacting protein kinase RIPK3." (PMID 25888634, 2015). "Furthermore, research has demonstrated that the low expression of RIPK3 and RIPK1, as observed through immunohistochemical staining, is associated with a worse prognosis in cervical cancer patients." (PMID 38338850, 2024). "As a special point, the expression status of RIPK3 in cervical carcinoma cells has also been shown to influence the efficacy of PolyI:C-induced immunotherapy, which facilitates the development of a more rational immunotherapy strategy based on the RIPK3 level." (PMID 38553639, 2024). "Significantly longer overall survival and progression-free survival rates could be detected in cervical cancer patients expressing nuclear RIPK1 or RIPK3 alone or simultaneously (RIPK1 and RIPK3)." (PMID 37197430, 2023). "Consistent with this study depicting necroptosis as a positive mechanism in cervical cancer, we found that patients with high nuclear RIPK3 expression, a key factor in the necroptotic pathway, had a significantly longer OS as well as PFS compared to patients with low expression of nuclear RIPK3." (PMID 37197430, 2023). "Caspase8 could promote necroptosis by stabilizing RIPK1 and necroptosis was reported to be induced by RETrA (REactivation of Transcriptional Reporter Activity) through the phosphorylation of RIPK1 and RIPK3 thus playing a therapeutic role in cervical cancer." (PMID 36357839, 2022). "Recently, using the model of cervical cancer, Smola demonstrated that PolyI:C driven immunogenicity strictly depends on the necroptosis regulator RIPK3 in neoplastic cells, suggesting RIPK3 as a novel predictive marker for personalization of cancer immunotherapy." (PMID 27429198, 2016). "Our findings suggest that the RIPK3 expression status in cervical cancer cells might critically influence the outcome of PolyIC-based immunotherapeutic approaches and should therefore be assessed prior to immunotherapy." (PMID 25888634, 2015). "RIPK3 expression status could critically influence immunotherapy of cervical cancer." (PMID 36357839, 2022). "Previous research, including our own, has shown that the expression of necroptosis-relevant proteins (RIPK1, RIPK3) correlates with a better OS and PFS in cervical cancer patients." (PMID 38338850, 2024). "In conclusion, this study showed that RIPK1 and RIPK3 correlated with longer OS and PFS in cervical cancer patients and can therefore be described as positive prognosticators for cervical cancer." (PMID 37197430, 2023).
cervical carcinoma (continued). "Necrosis of cervical cancer cells through phosphorylation of RIPK1, RIPK3, and MLKL, thereby triggering an antitumor immune response in cervical cancer." (PMID 36349142, 2022). "Multivariate Cox regression analysis was conducted to test for independent prognosticators for OS and PFS in the cohort of n = 250 cervical cancer patients and significantly showed nuclear co-expression of RIPK1 and RIPK3 as independent prognosticators for OS and PFS." (PMID 37197430, 2023). "Although RIPK3 contributes to the generation of active IL-1β in other cell types, the release of IL-1β from PolyIC-stimulated cervical cancer cells was negligible and did not contribute significantly to DC stimulation." (PMID 25888634, 2015). "This could indicate that cervical cancer cells are capable of inducing necroptosis, specifically in those where RIPK3 is not downregulated." (PMID 37197430, 2023). "High nuclear RIPK3 expression was significantly associated with lower FIGO classification, low extent of the primary tumor (pT1) and negative lymph node status (pN0) in cervical cancer." (PMID 37197430, 2023). "Hence, we conclude that downregulation of RIPK3 via hr-HPV has a negative prognostic impact on OS and PFS in cervical cancer patients." (PMID 37197430, 2023).
COVID-19 (15 papers, 2021 to 2024). A disease caused by infection with severe acute respiratory syndrome coronavirus 2. "Similarly, previous studies have demonstrated that the serum levels of RIPK3 were higher in 10 patients with COVID-19 and ARDS than in six with mild diseases, suggesting that RIPK3-mediated signal is associated with ARDS development in patients with COVID-19." (PMID 34594225, 2021). "Recent reports indicate that serum RIPK3 levels are elevated in patients with severe COVID-19 compared with those with milder ones, implying a potential role for RIPK3 in the progression from COVID-19 pneumonia to ARDS." (PMID 39516736, 2024). "With the triangles or RIPK3, the larger the triangle or the shape of RIPK3, the higher the severity of the COVID-19." (PMID 35632517, 2022). "This phenomenon reflects the discussions in the Introduction that RIPK3 is related to the natural essence of COVID-19, while ATP6V1B2, IFI27, BTN3A1, SERTAD4, and EPSTI1 contain more information about SARS-CoV-2." (PMID 36298522, 2022). "We found that the expression of RIPK3 was only detectable by IHC in a few macrophages and p-RIPK3 was undetectable in COVID-19-positive lung." (PMID 34663909, 2021). "In fact, serum level of RIPK3 is significantly higher in severe COVID-19 cases than in mild cases." (PMID 36499351, 2022). "As the vast majority of these data are correlative, based solely on in vitro findings or obtained using non-SARS-CoV-2 models, the exact role of necroptotic cell death vs. inflammatory signaling evoked by RIPK1 and/or RIPK3 remains to be established in COVID-19." (PMID 35244141, 2022). "Since the phosphorylation of MLKL is mediated by RIPK3 in necroptosis, the low-level expression of RIPK3 in COVID-19 lung may preclude the activation of MLKL downstream of activated RIPK1 to promote necroptosis." (PMID 34663909, 2021). "As RNA viruses can promote the inflammasome activation via RIPK1/RIPK3, Nec-1 may help in regulating this process by limiting inflammation and cytokines release induced by COVID-19." (PMID 34201847, 2021). "The plasma level of RIPK-3 was measured in a cohort of severe and mild COVID-19 patients." (PMID 34201847, 2021). "The deletion of both RIPK3 and caspase-8 is found to protect against cell death, not RIPK3 deficiency only, which shows that not only necroptosis but also other processes of cell death occur in COVID-19." (PMID 34594225, 2021). "As a result, it is safe to conclude that the five genes, ABCB6, KIAA1614, MND1, RIPK3, and SMG1, are truly COVID-19 specific, and the newly proposed classification method is a powerful tool." (PMID 35632517, 2022). "Junqueira at al identified increased expression of RIPK3, ZBP1 and Caspase-8 in blood samples of severe COVID-19 cases using expression quantitative trait loci (eQTLs) gene profiling." (PMID 35244141, 2022). "The absence of phosphorylation of RIPK1 or RIPK3 in the P21 infected mice provides additional evidence that SARS-CoV-2 does not induce necroptosis in the context of severe COVID-19." (PMID 38286985, 2024). "In this pathway, phosphorylation of receptor-interacting protein kinase-3 (RIPK3) and mixed lineage kinase domain-like (MLKL) also induces necroptosis and facilitates inflammation via IL-1β, which may be related to COVID-19-induced ARDS." (PMID 36499351, 2022). "The serum RIPK3 level is high in COVID-19 patients in severe cases but does not directly indicate necroptosis." (PMID 36090995, 2022). "Since MLKL is inducible by IFNγ in inflammatory hepatitis to promote inflammation in a RIPK3-independent fashion, MLKL may be induced by the inflammatory response in the COVID-19 lungs." (PMID 34663909, 2021). "In this scenario, the use of Nec-1/Nec-1 analogues might alleviate cytokine storm, systemic inflammation, and COVID-19 thanks to its activity to block RIPK1, the molecule that interacts with RIPK3 and promotes the phosphorylation of MLKL." (PMID 34201847, 2021).
COVID-19 (continued). "Interestingly, while neither the active/phosphorylated forms of RIPK3 nor MLKL were detectable in lungs of COVID-19 patients in this study, high gene expression levels of MLKL were identified in lung and airway epithelial cells, macrophages and neutrophils." (PMID 35244141, 2022). "This provides evidence that MLKL activation in COVID-19 may not occur downstream of activated RIPK1–RIPK3 to promote necroptosis, but rather by alternative RIPK3-independent inflammatory responses such as via IFNγ as previously reported in inflammatory arthritis." (PMID 35244141, 2022).
leukemia (15 papers, 2017 to 2025). A malignant (clonal) hematologic disorder, involving hematopoietic stem cells and characterized by the presence of primitive or atypical myeloid or lymphoid cells in the bone marrow and the blood. "Some leukemia-related mutations induce the activation of Ripk3 signaling in hematopoietic cells." (PMID 35561683, 2022). "For instance, ponatinib (targets both RIPK1 and RIPK3) and dabrafenib and Sorafenib (targets RIPK3) were approved for the treatment of leukemia." (PMID 38852117, 2024). "Inactivation of Ripk3 in HSCs accelerates low-dose IR-induced leukemia development in mice due to impairment of Mlkl necroptotic and PDC-OXPHOS-ROS senescence pathways in pre-LSCs." (PMID 35561683, 2022). "Activated Ripk3 signaling promotes the elimination of HSCs during serial transplantation and pre-leukemia stem cells (pre-LSCs) during fractionated IR by inducing Mlkl-dependent necroptosis." (PMID 35561683, 2022). "RIPK3 suppresses malignant myeloproliferation by activating the inflammasome, thus promoting differentiation and cell death, and RIPK3 expression is often reduced in primary de novo AML to prevent leukemia-initiating cells from dying." (PMID 33435298, 2021). "For example, RIPK3 expression is significantly reduced in leukemia cells of AML patients and in breast cancer tumors." (PMID 29527209, 2018). "We found that, during both serial transplantation and IR exposure, in addition to inducing Mlkl-necroptosis, thus reducing the number of HSCs, Tnf-α attenuates HSC functioning and represses IR-induced leukemia development primarily by stimulating Ripk3 signaling-mediated Mlkl-independent senescence." (PMID 35561683, 2022). "Similarly, another study also shows that knockout of RIPK3 in mice has markedly enhanced leukemogenesis by promoting the accumulation of leukemia-initiating cells and further connection between RIPK3 suppression and cell death blockage, which is also validated in primary AML patient cohorts." (PMID 36361505, 2022). "However, in response to serial transplantation, inactivation of Ripk3 signaling prevents stress-induced HSC exhaustion and functional HSC attenuation, while in response to fractionated low doses of ionizing radiation (IR), inactivation of Ripk3 signaling accelerates leukemia/lymphoma development." (PMID 35561683, 2022). "Ripk3 signaling represses the development of such sub-types of AML by stimulating Mlkl-mediated necroptosis and IL-1β-induced differentiation of pre-leukemia stem cells (pre-LSCs) as demonstrated in mouse models." (PMID 35561683, 2022). "To further characterize the RIPK3 epigenetic regulation, we used a pharmacological treatment of cell lines using 5-Aza-2′deoxycytidine (Aza), an FDA- and EMA-approved medication for certain leukemias." (PMID 38397165, 2024). "Previously, proteasome inhibition was shown to induce necroptosis in MEFs and human leukemia cells without the need of caspase inhibition and TNF stimulation, but through the accumulation of K48-poly-ubiquitinated RIPK3." (PMID 37495567, 2023).
ischemia (14 papers, 2018 to 2025). A hypoperfusion of the BLOOD through an organ or tissue caused by a PATHOLOGIC CONSTRICTION or obstruction of its BLOOD VESSELS, or an absence of BLOOD CIRCULATION. "In conclusion, our study was the first to demonstrate that p-RIPK1 (Ser166) increases in the brain after ischemia, which then activated the RIPK3/MLKL-dependent necroptotic signaling pathway to cause neuronal death." (PMID 31440386, 2019). "Studies have validated that the heart can be targeted to protect against ischemia- and oxidative stress-induced necroptosis and myocardial remodeling via the RIPK3–CaMKII–MPTP pathway." (PMID 38684668, 2024). "Although Caspase 8 expression was not affected by hyperoxia, its expression was significantly increased, especially in Ripk3−/− mice with ischemia and increased neovascularization during OIR." (PMID 39768199, 2024). "To date, most studies have shown that necroptosis is the cause of a majority of negative effects of cerebral ischemia; therefore, targeting or inhibiting the downstream regulator RIPK3 represents a novel therapeutic strategy for ischemia." (PMID 38684668, 2024). "RIPK3 mediates myocardial necroptosis through activation of calcium/calmodulin-dependent protein kinase II (CaMKII) in cardiac ischemia-reperfusion (I/R) injury and heart failure." (PMID 35805993, 2022). "In an in vitro model of cerebral ischemia, GSK’872, an inhibitor of RIPK3, administered after “ischemia” but during “reperfusion” increased HT-22 cell viability." (PMID 33142926, 2020). "In this study, we showed that p-RIPK1 (Ser166) induced by ischemia triggered the RIPK3/MLKL-dependent necroptotic pathway." (PMID 31440386, 2019). "We also demonstrated that ischemia-induced RIPK1-mediated RIPK3/MLKL necroptosis was specific because Nec-1 treatment could significantly inhibit ischemia-induced increase of RIPK3, MLKL and p-MLKL expressions as well as attenuate ischemic brain injury via inhibition of RIPK1 kinase activity." (PMID 31440386, 2019). "Necroptosis, a regulated form of necrotic cell death mediated by the RIPK3-MLKL axis, has recently emerged as a major contributor to cardiomyocyte death during ischemia-reperfusion injury, MI and heart failure." (PMID 41567640, 2025). "Multiple independent investigators have found that in vivo and in vitro, ischemia stimulates the upregulation and activation/phosphorylation of RIPK1, RIPK3, and MLKL." (PMID 33142926, 2020). "The levels of three core components of necrotic pathways, RIPK1, RIPK3 and MLKL significantly increased during 6–24 h of ischemia developed after the beginning of reperfusion, while cleaved caspase-8 was reduced." (PMID 30158627, 2018). "The process involves ischemia and oxidative stress-induced cardiac injury, as follows: the classical necroptotic pathway is usually initiated by the phosphorylation of RIPK1, which further phosphorylates RIPK3." (PMID 37383699, 2023). "It is therefore unclear if necroptosis or RIPK3-activation independent of cell death modulates the immune system and explains the protective effects of RIPK3-deficient mice in ischemic injury and other diseases, such as the TNFα-mediated shock (SIRS) or ischemia-reperfusion injury (IRI)." (PMID 29500402, 2018).